HLA-DRB1 (major histocompatibility complex, class II, DR beta 1)
Diseases named in the same sentence as HLA-DRB1 in open-access papers (continued):
Sharing a sentence is not in itself a finding about the gene and the disease.
cancer (continued). "Differential gene expression and gene ranking analyses revealed that the expression of CD74, HLA-DRA, HLA-DRB1, and FXYD3 was elevated in MHC-II+ cancer cells, whereas the expression of LOXL2 and DLL4 was increased in MHC-II− cancer cells." (PMID 41281745, 2025). "As for MHC molecules, we found the MHC class II molecules including HLA-DPA1, HLA-DPB1, HLA-DRA, HLA-DRB1, HLA-DQA1, HLA-DQB1 showed a stronger relation with PD-1 than other MHC molecules in some cancer types." (PMID 30607140, 2018). "Gene Ontology (GO) and Kyoto Encyclopedia of Genes and Genomes (KEGG) analyses revealed that the top upregulated genes (start vs. end) in cancer‐pre cells (Curve1 and Curve2) were enriched in antigen processing and presentation pathways, such as CD74, HLA‐DRB1, HLA‐DRA, PSME1/2, and CTSB." (PMID 40860436, 2025). "Besides, the somatic mutations of the organoids were identified and cancer mutant genes in the most relevant BC genes were also found, including ERBB4, HLA-DRB1, PDE4DIP, PTPN22." (PMID 32774159, 2020). "Notably, HLA-A, HLA-DPA1, HLA-DQB1, HLA-DRA, HLA-DRB1, HLA-DRB5, and HLA-J consistently negatively correlated with the PLK1 expression in the 12 cancer types." (PMID 30631355, 2018). "Based on our identification of the ectodomain of HLA-DRB1 in the CSF of PCNSL patients, we suggest an alternative mechanism of cancer-associated immune evasion, which, to our knowledge, has not been described so far." (PMID 29299134, 2017).
infectious disease (16 papers, 2007 to 2025). A disorder directly resulting from the presence and activity of a microbial, viral, or parasitic agent in humans. "Previous studies have reported associations between the HLA-DRB1*09:01 allele and infectious diseases." (PMID 39599823, 2024). "HLA-DRB1*13 alleles have been shown to play a protective role against multiple autoimmune and certain infectious diseases like HBV in HLA-Disease association studies." (PMID 35154160, 2022). "As expected, HLA-DRB1*12 was associated with protection against at least five infectious diseases, while HLA-DRB1*03 was associated with susceptibilities to eight infectious diseases, which is highly unlikely by chance (Fisher test, P = 0.003)." (PMID 30703088, 2019). "HLA-DRB1*12:02 is a promiscuous allele that has been associated with protection from certain infectious diseases." (PMID 30703088, 2019). "The polymorphic HLA-DRB1 has been associated with several complex and infectious diseases, such as acute coronary syndrome, HSV2 related meningitis, type I diabetes, celiac disease and multiple sclerosis." (PMID 24278156, 2013). "To investigate this issue, we focused on two geographically widespread allelic groups with exceptionally high (HLA-DRB1*12) and exceptionally low (HLA-DRB1*03) promiscuity values, respectively, and conducted literature mining on their reported associations with infectious diseases." (PMID 30703088, 2019). "HLA-DRB1 is a member of major histocompatibility complex Class II (MHCII), which is associated with autoimmune and infectious diseases and is a key player in the regulation of numerous immune responses." (PMID 32116649, 2020). "In addition, studies on MHC and infectious diseases have shown that MHC class II alleles; HLA-DRB1 and HLA-DQB1 have also been associated with more than 100 infectious diseases." (PMID 36161604, 2022). "Also, it is well known that HLA-DRB1*13 has a protective effect on infectious diseases." (PMID 39273401, 2024).
immune diseases (12 papers, 2015 to 2025). "HLA-DRB1 position 13 amino acid is associated with multiple immune system disorders, and was recently shown to be most strongly associated with individual differences in the T cell receptor complementarity determining region 3 (CDR3) repertoire." (PMID 36969218, 2023). "The beneficial effect exerted by the HLA-DRB1*11:01 allele can be discussed regarding its involvement in immune disease settings." (PMID 34497278, 2021). "Among these, variants in HLA-C, HLA-DQB1 and HLA-DRB1 genes were found, a very significant finding in view of the important contribution of the HLA complex to immune disease susceptibility and pathogenesis." (PMID 31511551, 2019). "HLA alleles play an important role in auto-immune diseases and the HLA families detected as eGenes from sun-exposed skin tissues were HLA-DQA1, HLA-DRB1, and HLA-DQB1." (PMID 31671645, 2019). "In diseases of the immune system, there were also highly relevant genes, such as HLA-DQA1, HLA-DRB1 and TYK." (PMID 36430729, 2022).
neurological diseases (7 papers, 2016 to 2024). "HLA-DRB1*03:01 TG mice actively immunized with hAQP4281-300, or with whole-length hAQP4 protein were resistant to developing a neurological disease that resembles NMO." (PMID 27054574, 2016). "Interestingly, several genes encoded in the HLA locus, which has been implicated in SCZ and other psychiatric and neurological disorders, were picked up by our inference downstream of the identified transcription factors (HLA-DOA, HLA-DOB, HLA-DRB1, HLA-DMA, and BRD2)." (PMID 36344995, 2022).
myopathy (4 papers, 2019 to 2025). A disease of the muscle in which the muscle fibers do not function properly. "In contrast, HLA-DRB1*11:01 is known to increase the risk of anti-HMGCR myopathy in adult patients." (PMID 35672822, 2022). "Interestingly, HLA-DRB1*11:01 has been significantly associated with anti-HMGCR myopathy with estimated OR of ~25–57 dependent on ethnicity." (PMID 33198260, 2020). "The immune system is implicated in both conventional statin intolerance/myotoxicity via LILRB5 rs12975366, and a strong association exists between HLA-DRB1*11:01 and anti-HMGCR positive myopathy." (PMID 31861911, 2019). "Whilst the association between HLA-DRB1*11:01 and anti-HMGCR positive myopathy is notably strong, HLA-DRB1*11:01 will likely be insufficient to predict this condition alone given its rarity, but HLA-DRB1*11:01 may have utility in excluding the diagnosis." (PMID 31861911, 2019). "Importantly, HLA-DRB1*11:01 has been significantly associated with anti-HMGCR positive myopathy, and the ORs for the presence of HLA-DRB1*11:01 in anti-HMGCR myopathy white or black patients, compared to controls, have been estimated to be ~25 and ~57, respectively." (PMID 31861911, 2019).
adenocarcinoma (3 papers, 2017 to 2021). A common cancer characterized by the presence of malignant glandular cells. "A strongly reduced risk of adenocarcinoma was seen with HLA-DRB1*13 (OR = 0.54, P = 1.83 × 10−5)." (PMID 28806749, 2017). "Thus, controlling for the amino acid positions 13 and 71 in HLA-DRB1, and position 156 in HLA-B, no residual HLA allele or amino acid associations are observed with adenocarcinoma (P > 0.001)." (PMID 28806749, 2017).
cardiovascular disease (3 papers, 2012 to 2023). "Other studies showed various HLA-DRB1 alleles could contribute differently to susceptibility of cardiovascular disease." (PMID 32455133, 2020). "Hence, it should be stressed that the data reported here confirm the association between HLA-DRB1*04 and cardiovascular disease risk in patients from the Brazilian Amazon." (PMID 22912672, 2012). "However, we can assume that in this case the association between HLA-DR4 and increased risk for cardiovascular disease in RA is mainly due to HLA-DRB1*04 and that shared epitope alleles are involved in susceptibility to RA." (PMID 22912672, 2012). "However, the results of the statistical analysis strongly supports the claim that HLA-DRB1*04 is associated with increased risk for cardiovascular disease in RA." (PMID 22912672, 2012). "Our findings demonstrated a potentially protective role of HLA-DRB1 against the development of cardiovascular disease in patients with T2D." (PMID 32455133, 2020).
connective tissue disease (3 papers, 2020 to 2025). "Allelic variations in the HLA-DRB1*11 gene have shown different associations in this patient group, such as HLA-DRB1*08:03 in patients with prior statin use and HLA-DRB1*11:01 in patients with paraneoplastic disease or coexisting connective tissue disorders." (PMID 41303626, 2025).
hematologic diseases (3 papers, 2016 to 2024). "All patients were to receive either peripheral blood or bone marrow allo-HSCT for hematologic malignancy from unrelated donors who were 8 of 8 or 7 of 8 human leukocyte antigen (HLA)-matched (a single allele mismatch at HLA-A, HLA-B and HLA-C, and HLA-DRB1 was permitted)." (PMID 38844797, 2024). "Furthermore, we showed that some HLA alleles are increased in various hematologic diseases; in particular, that HLA-DRB1*08:02:01G is significantly increased in MDS patients compared with the general Korean population." (PMID 35626230, 2022).
neurodegenerative disease (3 papers, 2022 to 2023). A disorder of the central nervous system characterized by gradual and progressive loss of neural tissue and neurologic function. "This process was accompanied by increased expression of CLU, a gene involved in cell death and neurodegenerative diseases, and decreased expression of the immune genes HLA-DRA, HLADRB1 and CD74." (PMID 37275903, 2023).
bacterial infection (1 paper, 2025). "We showed that the median expression of certain genes (IFI27, HLA-DRB1, USP18, STAP1, and OAS3) in the Biomeme HR-B/V classifier was higher in viral versus bacterial infection." (PMID 41496780, 2025).
genetic disease (1 paper, 2010). "When considering these results in the context of human mate selection, it is important to note that MS is a complex genetic disease strongly associated with the MHC class II gene HLA-DRB1." (PMID 21067613, 2010).
skin disorder (1 paper, 2025). Any deviation from the normal structure or function of the skin or subcutaneous tissue that is manifested by a characteristic set of symptoms and signs. "In the HLA-DRB1 locus, the alleles HLA-DRB1*07:13, DRB1*01:13, and DRB1*04:11 were observed less frequently in the research group than in the control group, suggesting their potential protective effect in the case of HIV infection with respect to HIV-associated skin disorders." (PMID 40572779, 2025).
HLA-DRB1 also shares sentences with these, for which no sentence is quoted: celiac disease (12 papers); colitis (5); giant cell arteritis (5); psychiatric disorder (5); ankylosing spondylitis (4); autoimmune Addison’s disease (4); hepatitis C (4); IgA nephropathy (4); renal disease (4); atopic dermatitis (3); Cognitive impairment (3); hairy cell leukemia (3); Immunodeficiency (3); juvenile idiopathic arthritis (3); lymphoproliferative disorders (3); Moyamoya disease (3); spondyloarthritis (3); adult-onset Still disease (2); AIDS (2); alopecia (2); anaphylaxis (2); aneurysm (2); aortic aneurysm (2); autoimmune encephalitis (2); duodenal ulcer (2); granulomatosis with polyangiitis (2); Guillain-Barre syndrome (2); hypophysitis (2); liver cirrhosis (2); macrophage activation syndrome (2).
A further 139 diseases each share a sentence with HLA-DRB1 in 2 papers or fewer.